LAD1 (ladinin 1)
Description:
Anchoring filament protein which is a component of the basement membrane zone.
Synonyms: LADA
Tractability: Antibody: UniProt places it where antibodies can reach, with medium confidence; its Gene Ontology location is reachable by antibodies, with medium confidence. PROTAC: its protein half-life has been measured.
Gene: Protein-coding gene on chromosome 1 (201,380,833 to 201,399,915, reverse strand). Ensembl gene ENSG00000159166.
Subcellular location: Secreted, extracellular space, extracellular matrix, basement membrane
Subcellular location (Human Protein Atlas): Actin filaments; Predicted to be secreted
Gene Ontology:
Molecular function: cadherin binding; structural molecule activity
Cellular component: actin cytoskeleton; extracellular exosome; basement membrane
Genetic constraint (gnomAD): Loss-of-function variants: 54 observed, 53.78 expected, observed/expected ratio (o/e) 1, 90% interval 0.81 to 1.26. The upper end of that interval is the gene's LOEUF score, 1.26, which puts it in group 5 of 6, group 1 being the genes least tolerant of losing a copy. Missense variants: 637 observed, 650.86 expected, observed/expected ratio (o/e) 0.98, 90% interval 0.92 to 1.04. Synonymous variants: 231 observed, 255.3 expected, observed/expected ratio (o/e) 0.9, 90% interval 0.81 to 1.01.
Homologues: Orthologues: chimpanzee LAD1 (96% identical), macaque LAD1 (94% identical), mouse Lad1 (68% identical), rat Lad1 (66% identical), rabbit LAD1 (64% identical), guinea pig LAD1 (62% identical).
Diseases named in the same sentence as LAD1 in open-access papers:
LAD1 is named in the same sentence as 60 diseases in open-access papers, as found by Europe PMC text mining. Sharing a sentence is not in itself a finding about the gene and the disease. The quoted sentences say what the papers report.
breast carcinoma (8 papers, 2012 to 2025). "Similar associations have been observed in prostate cancer and breast cancer, where LAD1 expression correlates with poor prognosis and drug resistance." (PMID 41423496, 2025). "An analysis of METABRIC, a large clinical dataset of approximately 2000 breast cancer patients, demonstrates that a high abundance of the LAD1 transcript is associated with poor prognosis in breast cancer patients." (PMID 36770773, 2023). "Moreover, analysis in METABRIC, a large clinical dataset of approximately 2000 breast cancer patients, showed that a high abundance of LAD1 transcripts is associated with poor prognosis in breast cancer patients." (PMID 33267790, 2020). "LAD1 was found to be a tumorigenesis factor in multiple cancers, such as colorectal cancer, prostate cancer, breast cancer, etc10–13." (PMID 41423496, 2025). "At present, some articles have shown that LAD1 is expressed in some cancers, such as colorectal cancer, prostatic cancer, laryngeal cancer, and breast cancer, demonstrating that LAD1 expression is related to cancer migration and invasion." (PMID 36770773, 2023). "Ladinin‐1(Lad1), a largely uncharacterized protein to date, was found to be related to the proliferation and migration of breast cancer cells (Roth, Srivastava, & Lindzen, 2018)." (PMID 31958216, 2020). "Another study showed that LAD1 may be downstream of EGF signaling to regulate the oncogenic behaviors of mammary tumors." (PMID 36770773, 2023). "As previous studies, LAD1 mediates the proliferation and migration of breast cancer cells." (PMID 33536022, 2021). "We were able to show that FXYD3 and PTX3 expression is associated with poor overall patient survival in SCC patients and LAD1, SLC7A5, SLPI, NID2, SPOCK1 and SULF1 correlated significantly with impaired pCR in breast cancer patients." (PMID 23251436, 2012). "Furthermore, LAD1 has been reported as a filament-binding regulator and also regulates EGF signaling-mediated breast cancer tumorigenesis." (PMID 31164716, 2020). "From the downregulated genes of the EMT-core gene list, low FXYD3 expression showed a trend to poor overall survival of SCC patients (p = 0.17) and low expression of LAD1 (p = 0.00074), SLC7A5 (p = 0.0093) and SLPI (p = 0.043) significantly correlated with worse pCR of breast cancer patients." (PMID 23251436, 2012).
lung carcinoma (7 papers, 2020 to 2025). "In lung tissues, LAD1 exhibited moderate expression in normal lung tissues, but its expression in lung cancer was relatively high compared to other types of cancer." (PMID 41423496, 2025). "We firstly tested LAD1 expression in ten lung cancer cell lines, including one LUSC, one LCLC (large cell lung cancer), and eight LUADs." (PMID 36770773, 2023). "Considering the importance of the EGF signaling pathway in the development of lung cancer, does LAD1 participate in EGF signaling to regulate lung cancer development?" (PMID 36770773, 2023). "This study provides evidence that LAD1 is a potential target for developing therapeutic agents for lung cancer." (PMID 36613882, 2022). "It is suggested that LAD1 expression is negatively correlated with OS and FP in lung cancer patients." (PMID 36613882, 2022). "After recording the overexpression of LAD1 mRNA and protein in tumor parts, we explored its prognostic role in lung cancer using the KM plotter." (PMID 36613882, 2022). "The GSEA of the LAD1-correlated gene set strongly associated with cell proliferation, EMT, and metastasis in LUAD indicated that LAD1 lung cancer growth by regulating the cell cycle." (PMID 36613882, 2022). "As with LAD1, poor clinical outcomes were significantly associated with increased B3GNT3 expression in lung cancer patients." (PMID 36613882, 2022). "This study reveals that LAD1 plays a major role in regulating proliferation and migration in lung cancer and impacts survival in LUAD." (PMID 36613882, 2022). "One is Ladinin-1, a basement membrane protein probably involved in lung cancer formation." (PMID 38473953, 2024). "Nonetheless, the molecular function of LAD1 in the progression of lung cancer remains elusive." (PMID 36613882, 2022). "Our study indicates that LAD1 acts as an oncogene in lung cancer development." (PMID 36613882, 2022). "Taken together, the results of our study provided evidence that the upregulation of LAD1 and B3GNT3 in LUAD and is a possible mechanism related to the increased mesenchymal phenotype in lung cancer and to the remodeling of the tumor microenvironment." (PMID 36613882, 2022). "Compatible with the survival analysis in lung cancer, the GSEA revealed that high expression levels of LAD1 were correlated with a poor prognosis in LUAD." (PMID 36613882, 2022). "The expression of LAD1 is regulated by miR-331, which is downregulated in A549 and PC9 lung cancer cells." (PMID 36613882, 2022). "Compared with normal tissues, the expression of ADM2, CLIC6, KIF20A, LAD1, MUC5B, and TNS4 was up-regulated, and the expression of ATG16L2, KCNK3, MAFF, NKD1, and SPATA13 was down-regulated in lung cancer tissues." (PMID 34804921, 2021). "In contrast, PROM2 was significantly co-expressed with LAD1, C1ORF106, PVRL4, and KCNK5 in lung cancer." (PMID 31164716, 2020). "We also innovatively proposed that LAD1 may assign a “K-Ras addiction” phenotype to LUAD tumor cells, and EGF signal activation closely related to lung cancer may belong to one of the carcinogenic signaling pathways." (PMID 36770773, 2023). "The survival analyses from the KM plotter revealed lower OS and FP, but this was not the case for PPS in lung cancer patients with high LAD1 expression." (PMID 36613882, 2022). "In addition, studies assessing the involvement of LAD1 in lung cancer progression are lacking." (PMID 36613882, 2022). "There was a significant negative correlation between LAD1 expression and methylation levels in LUAD, but not in LUSC, another lung cancer subtype (p = 1.88 × 10−5)." (PMID 36770773, 2023).
breast tumors (5 papers, 2020 to 2023). "Noteworthy among them: overexpression of Ladinin-1 (LAD1), a known 59 kDa protein, has been associated with aggressive breast tumors and poor prognosis." (PMID 37046807, 2023). "A recent study found that LAD1 is associated with malignant and aggressive human breast tumors, and the authors have proved through in vitro studies, animal models, and clinical data that the widespread expression of LAD1 acts as a substrate for the downstream phosphorylation of the EGF pathway." (PMID 36770773, 2023). "The same study also reported that LAD1 physically interacted with stratifin (14–3-3σ), which promoted breast tumor invasion by regulating actin filament turnover." (PMID 33267790, 2020). "LAD1 was identified recently as an interactor of FLNA in mammary cells and may be a marker of aggressive breast tumors." (PMID 33266100, 2020).
colorectal cancer (5 papers, 2020 to 2025). A primary or metastatic malignant neoplasm that affects the colon or rectum. "Depletion of LAD1 prevents colorectal cancer cells from migrating to the liver in vivo, and increased LAD1 expression is linked to metastatic colorectal cancer tissues." (PMID 37718450, 2023). "We constructed LAD1-depleted cell lines and examined the effect of LAD1 deficiency on the phenotypic and molecular features of colorectal cancer cells in vitro." (PMID 33267790, 2020). "Here, to determine the relationship of LAD1 with colorectal cancer progression, we explored the effect of LAD1 loss on the malignant features of colorectal cancer cells." (PMID 33267790, 2020). "In colorectal cancer, upregulated LAD1 has been identified as a significant hazard prognostic factor associated with enhanced metastasis." (PMID 41423496, 2025). "For example, transcriptomic studies have demonstrated that LAD1 mRNA is expressed at higher levels in tumor tissue and that its up-regulation is correlated with poor survival in breast cancer, colorectal cancer, and prostate cancer." (PMID 36613882, 2022). "Regarding the promoting effect of cancer, Lad1 is reported to enhance the migration and invasion of colorectal cancer cells and facilitate further metastatic progression in a mouse model." (PMID 36613882, 2022). "Together, these results imply that LAD1 is functionally involved in the metastatic motility of colorectal cancer cells to invade through the extracellular barrier." (PMID 33267790, 2020). "To determine the clinical relevance of LAD1 to colorectal cancer, we assessed the correlation of LAD1 mRNA levels with the clinical outcome of colorectal cancer patients." (PMID 33267790, 2020). "However, the association of LAD1 with colorectal cancer remained unknown." (PMID 33267790, 2020). "In this study, we suggest LAD1 as a positive regulator of the metastatic progression of colorectal cancer." (PMID 33267790, 2020). "To verify the association of LAD1 with the metastatic progression of colorectal cancer in humans, we examined the level of LAD1 protein in colorectal cancer tissues." (PMID 33267790, 2020). "It is notable that overexpression of ectopic LAD1 increased the migration and invasion of SW480 in which endogenous LAD1 expression was largely lower than the other colorectal cancer cells." (PMID 33267790, 2020). "Comparative analysis of matched normal and cancer tissues showed a similar bias of strong LAD1 staining intensity toward colorectal cancer (0% vs 43% in normal and cancer tissues, respectively)." (PMID 33267790, 2020). "Future studies exploring the molecular mechanism by which LAD1 regulates the metastatic capability of colorectal cancer cells will help to expand the repertoire of possible therapeutic approaches to overcome colorectal cancer metastasis." (PMID 33267790, 2020). "This indicates that LAD1 depletion compromised the potential of colorectal cancer cells to metastasize for proliferation in the liver." (PMID 33267790, 2020). "To explore the molecular mechanisms involved in the regulation of colorectal cancer cell motility by LAD1, we first determined the effect of LAD1 on the expression of epithelial-mesenchymal transition (EMT) markers." (PMID 33267790, 2020). "To corroborate the functional involvement of LAD1 in colorectal cancer metastasis, we established a metastasis model in nude mice." (PMID 33267790, 2020). "In this study, we aimed to explore the expression of LAD1 and its functional involvement in colorectal cancer progression by using cell-based systems and a xenograft mouse model." (PMID 33267790, 2020). "Immunohistochemistry of colorectal cancer tissues revealed LAD1 enrichment in metastatic tissues compared to that in primary tumor and normal tissues." (PMID 33267790, 2020).
colorectal cancer (continued). "To gain a better understanding of the function of LAD1 in colorectal cancer, we investigated genes in GSE14333 and GSE24549 whose expression was positively correlated with LAD1 expression (R > 0.4, p < 0.001)." (PMID 33267790, 2020). "Then, to gain insight into the biological function of LAD1 in colorectal cancer cells, we determined the cellular localization of LAD1." (PMID 33267790, 2020). "LAD1 protein expression in colorectal cancer patient specimens was assessed by immunohistochemistry of tumor microarrays." (PMID 33267790, 2020). "Accordingly, we decided to examine whether LAD1 expression is involved in the viability and growth of colorectal cancer cells." (PMID 33267790, 2020). "We detected substantial expression of LAD1 in different colorectal cancer cell lines except SW480." (PMID 33267790, 2020). "We found that LAD1 was abundant in most colorectal cancer cells." (PMID 33267790, 2020). "This indicates that LAD1 is dispensable for colorectal cancer cell survival." (PMID 33267790, 2020). "LAD1 depletion inhibited the migration and invasion of two different colorectal cancer cell lines, SW620 and Caco-2, without affecting their proliferation." (PMID 33267790, 2020). "Thirty-one percent of colorectal cancer tissues (11/35) exhibited strong LAD1 staining, whereas none of the normal tissues (0/9) displayed strong LAD1 signals." (PMID 33267790, 2020). "In addition, studies assessing the involvement of LAD1 in colorectal cancer progression are lacking." (PMID 33267790, 2020).
lung adenocarcinoma (4 papers, 2021 to 2025). A carcinoma that arises from the lung and is characterized by the presence of malignant glandular epithelial cells. "In lung adenocarcinoma tissues, LAD1 was significantly upregulated, particularly in the cancer cell subgroup within tumors." (PMID 41423496, 2025). "Although a comparative proteomic analysis found that LAD1 was abundant in lung adenocarcinoma, the exact role of LAD1 in LUAD remains to be explored." (PMID 36770773, 2023). "In this study, we conducted a series of studies on the oncogenic role of LAD1 in lung adenocarcinoma (LUAD)." (PMID 36770773, 2023). "The expression of LAD1 protein was further analyzed by immunohistochemistry and the results showed that LAD1 expression was strongly positive in the cytoplasm of lung adenocarcinoma cells." (PMID 36770773, 2023). "Transcriptomic and proteomic studies have demonstrated that LAD1 is also abundant in lung adenocarcinoma." (PMID 36613882, 2022). "Subsequent functional experiments showed that LAD1 knockdown decreased the cell migration of lung adenocarcinoma cells by regulating EMT." (PMID 36613882, 2022). "The greater the expression of LAD1 was, the shorter the duration of lung adenocarcinoma (LUAD) patient survival." (PMID 36613882, 2022). "Collectively, epigenetic and posttranscriptional modifications of LAD1 in lung adenocarcinoma may be beneficial to tumorigenesis." (PMID 36770773, 2023). "We hypothesized that LAD1 overexpression-mediated K-Ras addiction in lung adenocarcinoma may integrate with EGF signaling and influence its common downstream effector." (PMID 36770773, 2023). "Therefore, the present study aims to survey the expression pattern, the associated functional pathways, and possible regulatory mechanisms of LAD1 in lung adenocarcinoma." (PMID 36613882, 2022). "Thus, the hyperphosphorylation of LAD1 may be related to the occurrence and development of lung adenocarcinoma." (PMID 36770773, 2023). "Moreover, higher expression levels of LAD1 in lung adenocarcinoma also confers a poor prognosis." (PMID 36613882, 2022).
immune deficiency (3 papers, 2012 to 2024). "Based on our experience, FCM provided direct diagnostic insights for immunodeficiencies such as SCID, OS, MHC-II deficiency, WAS, XLA, XL-CGD, FHL, LAD-1, AR-CD46 deficiency, and CD55 deficiency." (PMID 39072316, 2024). "LAD1 patients suffer from a severe immunodeficiency due to an absence of functional CD18 heterodimers." (PMID 22474478, 2012).
prostatic cancer (3 papers, 2021 to 2025). "Therefore, we selected LAD1 as a potential target gene for docetaxel resistance development in prostate cancer." (PMID 34516317, 2021).
thyroid cancer (3 papers, 2015 to 2020). "Similarly, compared with normal tissues, the expression of the LAD1 transcript was elevated in human thyroid cancers carrying oncogenic mutations in genes such as BRAF, RET and RAS." (PMID 33267790, 2020). "A study of mouse thyroid cancer models revealed a molecular link between LAD1 expression and oncogenic signaling pathways in cancer by showing that the BRAFV600E mutation induced the expression of LAD1 transcripts." (PMID 33267790, 2020). "Anchoring filament protein ladinin-1 (LAD1) was related to the aggressive progression of breast, lung, laryngeal and thyroid cancers." (PMID 33267790, 2020). "LAD1 has been identified as an overexpressed gene in BRAFmut thyroid carcinomas compared to those with a RET/PTC rearrangement." (PMID 25922907, 2015).
metastatic colorectal cancer (2 papers, 2020 to 2023). "Collectively, these results suggest that the expression of LAD1 protein is positively associated with metastatic colorectal cancer progression." (PMID 33267790, 2020). "Although understanding the exact function of LAD1 requires additional studies in future, our findings in this study suggest that LAD1 has a potential being a prognostic biomarker for metastatic colorectal cancer." (PMID 33267790, 2020). "In addition, enhanced LAD1 staining in metastatic tumor tissues suggests that LAD1 is possibly involved in the progression of metastatic colorectal cancer." (PMID 33267790, 2020).
renal cell carcinoma (2 papers, 2017 to 2021). "LAD1 is identified as a potential marker in renal cell cancer, showing univariate association with distinct metastasis." (PMID 28678795, 2017). "Moreover, LAD1 promoter methylation is a promising prognostic marker for renal cell carcinoma." (PMID 33536022, 2021).
Autoimmunity (1 paper, 2022). The occurrence of an immune reaction against the organism's own cells or tissues. "To understand the role of Treg in LAD-1 development and manifestation of autoimmunity, we generated mice specifically lacking CD18 on Treg (CD18Foxp3), resulting in defective LFA-1 expression." (PMID 36346673, 2022).
bullous disorder (1 paper, 2023). "Moreover, LABD autoantibodies preferably react to LABD-97 than to LAD-1 leading to linear IgA bullous disorder (LABD)." (PMID 37803411, 2023). "Type XVII ectodomain cleavage occurs at different sites in the NC16A domain originating a 120 kDa fragment known as LAD-1, and autoimmunity towards this shed fragment of type XVII collagen induces bullous pemphigoid (BP)." (PMID 37803411, 2023).
diffuse large B-cell lymphoma (1 paper, 2025). "In terms of overall survival (OS), LAD1 was a significant hazard factor for LUAD and thymoma (THYM) but a beneficial factor for lymphoid neoplasm diffuse large B-cell lymphoma (DLBCL) and kidney renal clear cell carcinoma (KIRC)." (PMID 41423496, 2025). "Our results indicated that LAD1 was a significant hazard factor for overall survival (OS) in LUAD and thymoma (THYM), while showing beneficial effects for lymphoid neoplasm diffuse large B-cell lymphoma (DLBC) and kidney renal clear cell carcinoma (KIRC)." (PMID 41423496, 2025).